ABCA1 (ATP binding cassette subfamily A member 1)
Diseases named in the same sentence as ABCA1 in open-access papers (continued):
Sharing a sentence is not in itself a finding about the gene and the disease.
Obesity (continued). "Their reduced expression could be due to the increased serum LPS levels found in obesity, which repress the expression of LXR and, consequently, of ABCA1/ABCG1." (PMID 39062791, 2024). "In addition, LXRα, ABCA1, and ABCG1 expressions were negatively correlated with several obesity-related variables, such as weight, BMI, and hip circumference, reinforcing their association with obesity." (PMID 39062791, 2024). "Since ABCA1 has demonstrated roles in various GDM-related traits, such as lipid levels, obesity-related phenotypes, and insulin secretion and sensitivity, it may be a strong candidate gene for predisposition to GDM." (PMID 34975757, 2021). "It has been confirmed in mouse models that a lack of adipocyte-specific ABCA1 leads to obesity." (PMID 32774439, 2020). "Therefore, it appears that n-3 PUFA high fat diets may enhance the hepatic ABCA1-mediated efflux of cholesterol and phospholipids to apoA-1 containing nascent HDL particles in obesity-insulin resistance rats." (PMID 27101976, 2016). "HDL-leukocyte interactions via ABCA1 further modify cellular cholesterol flux and inflammatory potential; therefore, dietary strategies that alter HDL-leukocyte dynamics may have profound effects on obesity-related disease progression." (PMID 25045936, 2014). "The SNPs of ABCA-1 (LDL-C and ApoA1/ApoB); LIPC (TC, LDL-C, ApoA1 and ApoB); LIPG (ApoB); MTHFR (TC, TG and LDL-C); MYLIP (TC and TG); PCSK9 (TG, HDL-C, ApoB and ApoA1/ApoB); PPARD (TG and ApoA1/ApoB); and SCARB1 (TG, ApoA1 and ApoB) interacted with overweight/obesity to modulate serum lipid levels." (PMID 23039238, 2012). "However, the regulation of ABCA1 on level of HDL-C in obesity has not been clearly defined yet." (PMID 26828509, 2016). "ABCA1 mRNA expression had a significant negative correlation with HOMA-IR (r = −0.44, p = 0.0003) and adipose tissue insulin resistance index (adipo-IR, r = −0.35, p =0.005) in patients with obesity (mean BMI = 44.5 kg/m2)." (PMID 39063184, 2024). "In addition, four peptides derived from the ATP binding cassette subfamily A member 1 (ABCA1), apolipoprotein B (APOB), and cAMP response element-binding protein (CREB) showed potential in the treatment of obesity; however, they were not pharmacologically analyzed." (PMID 32121443, 2020).
coronary artery disease (60 papers, 2005 to 2025). "Several SNPs in ABCA1 have shown a strong association between plasma lipid levels and coronary heart disease susceptibility, while others were associated with a protective role." (PMID 37048678, 2023). "Studies on SNPs in the ABCA1 coding region have shown different associations between plasma lipid levels and coronary heart disease (CHD) susceptibility." (PMID 35743794, 2022). "Methylation of ATP binding cassette subfamily G member 1 (ABCG1) and ATP binding cassette subfamily A member 1 (ABCA1) has been associated with coronary heart disease." (PMID 36032780, 2022). "Less common alleles of −565C/T and −191G/C polymorphisms in the promoter of ABCA1 also predicted a lower risk of coronary heart disease." (PMID 34940525, 2021). "rs2230806 is also the most widely studied common missense polymorphism, and studies in Asians reported that ABCA1 SNP (rs2230806, also known as R219K or G1051A) is associated with type 2 DM and coronary heart disease." (PMID 33426085, 2020). ": Interaction between coronary artery disease and some acquired risk factors on the ABCA1 DNA methylation status." (PMID 30046619, 2018). "The authors confirmed in a second independent study that DNA methylation levels at the ABCA1 gene promoter locus are associated with aging and coronary artery disease in men." (PMID 28881789, 2017). "Numerous studies have focused on the association of ABCA1 gene polymorphism, serum lipid levels, and coronary heart disease, however, few studies have examined the relationship between ABCA1 gene polymorphisms and other diseases." (PMID 26891315, 2016). "Association of the R230C/ABCA1 variant with premature coronary artery disease and subclinical artherosclerosis." (PMID 23152888, 2012). "This is the first study assessing the effect of the R230C/ABCA1 variant in premature coronary artery disease." (PMID 23152888, 2012). "Univariate logistic regression showed that ABCA1 rs1883025 CT genotype is associated with decreased risk for coronary artery disease development under overdominant genetic model (OR = 0.498, 95% CI 0.254–0.976; p = 0.042) and codominant genetic model (OR = 0.468, 95% CI 0.232–0.945, p = 0.034)." (PMID 37587376, 2024). "Thus, the present study investigated the association between promoter methylation status of ABCA1 and inflammation in the development of premature coronary artery disease (pCAD)." (PMID 33557767, 2021). "Additionally, ABCA1 gene mutations have also been associated with decreased risk factors for coronary artery disease (CAD), another common vascular condition." (PMID 32292824, 2020). "Additionally, some studies report that the genetic variants of ABCA1 are significantly associated with an individual's risk of developing coronary artery disease." (PMID 33426085, 2020). "Additionally, ABCA1 genetic variants are strongly associated with the risk of coronary artery disease." (PMID 29681863, 2018). "Associations of the R230C/ABCA1 variant with metabolic risk factors for coronary artery disease." (PMID 23152888, 2012). "The K allele of ABCA1 gene may be protective factors of phlegm syndrome and blood stasis syndrome in coronary heart disease." (PMID 22690243, 2012). "In addition, the r219k polymorphism of the ABCA1 gene may influence the hypolipidemic effect of pravastatin in patients with coronary heart disease." (PMID 36011386, 2022). "In addition, methylation levels of the ABCA1 promoter may be associated with inflammation and the development of premature coronary heart disease." (PMID 36011386, 2022).
coronary artery disease (continued). "Other mechanisms explaining the association of high HDL-C and CVD, include genetic variants, e.g. CETP, ABCA1, LIPC, SCARB1, that lead to extremely high HDL-C concentrations and a higher risk of coronary artery disease and death." (PMID 41239356, 2025). "GREX of ABCA1 and CXCL12 was significantly associated with atherosclerotic phenotypes, including ischemic heart disease and coronary atherosclerosis in individuals of European genetic ancestry (n=65, 364, p<0.0044)." (PMID 39483879, 2024). "Acetylsalicylic acid (ASA) treatment can decrease ABCA1 DNA methylation level, thereby reducing the occurrence of atherosclerosis and coronary heart disease." (PMID 35752619, 2022). "Polymorphism in the ABCA1 gene is reportedly related to HDL-C deficiency, which leads to coronary heart disease or coronary artery disease." (PMID 33967955, 2021). "A decrease in the level of ABCA1 mRNA was also recently found in the peripheral blood mononuclear cells (PBMCs) of patients with coronary artery disease." (PMID 34940525, 2021). "A previous observational study showed that a 50% increase in ABCA1-mediated cholesterol efflux caused a 30% increase in the concentration of HDL-C, thus resulting in a decreased incidence of coronary artery disease (CAD) by 50%." (PMID 34575660, 2021). "A rs2230806 genetic variation of ABCA1 was significantly related to the development and severity of coronary artery disease (CAD) in an Iranian population." (PMID 33897762, 2021). "ABCA1 is also involved in coronary heart disease (CHD), type 2 diabetes (T2D), thrombosis, age-related macular degeneration (AMD), glaucoma, viral infections, and neurological disorders, such as traumatic brain injury, Alzheimer’s disease, and Parkinson’s disease." (PMID 38674035, 2024). "Increased ABCA1 promoter methylation level may result in the progression of coronary artery disease." (PMID 33557767, 2021). "Moreover, DNA methylation of multiple genes (i.e. ABCA1, ABCG1, LIPC, PLTP, CETP, and LPL) were associated with lipid traits and coronary artery disease outcomes (i.e. ABCA1) in patients with molecularly proven FH." (PMID 33096472, 2020). "According to recent studies, it has been revealed that the effects on plasma HDL cholesterol level and the incidence and severity of coronary heart diseases depend mostly on the distribution and frequency of SNPs in different regions of the ABCA1 gene as well as different populations." (PMID 33066695, 2020). "Dysregulation of miRs targeting ABCA1 can affect cholesterol homeostasis and contribute to coronary artery disease (CAD)." (PMID 39201292, 2024). "It was shown that ABCA1 promoter methylation levels were positively associated with serum inflammatory factors (CRP, IL-1β), circulating free DNA/neutrophil extracellular traps (cfDNA/NETs), suggesting a role for inflammatory responses in premature coronary heart disease." (PMID 36011386, 2022). "Mutations in ABCA1 may cause HDL-C deficiency and premature coronary artery disease (CAD)." (PMID 31039173, 2019). "Overall, as changes in the ABCA1 gene negatively influence cellular cholesterol uptake, the concentration of HDL-C decreases more sharply and the incidence of coronary artery disease (CAD) increases." (PMID 36651718, 2023). "This study showed how that the relation between ABCA1-CEC and incident coronary heart disease events were independent of multiple cardiovascular risk factors and remained significant after adjustment for HDL-C and ApoA-I." (PMID 40709204, 2025). "Moreover, serum levels of miR-27a were found to be inversely related to two cholesterol transporters: ABCA1 and ABCG1 gene expression in coronary heart disease patients." (PMID 37628623, 2023).
coronary artery disease (continued). "On the contrary, the association of ABCA1 rs2230806 polymorphism and HDL-C levels not observed in young Greek nurses and coronary heart disease patients." (PMID 26891315, 2016). "In fact, this idea has already been raised by other researchers concluding that ROS may promote coronary artery disease by counteracting the established anti-atherogenic effects of HDL and ABCA1 pathways on the human artery wall." (PMID 23115616, 2012).
diabetes (60 papers, 2008 to 2025). "Additional investigations of other diabetes-associated SNPs, including the recently reported polymorphism rs1800977 (C69T) within the ATP-binding cassette transporter A1 (ABCA1) gene are necessary." (PMID 35164795, 2022). "The strong evidence supporting a causal role for dyslipidemia in diabetes comes from genetic studies of rare mutations in ABCA1, LIPE, LPL, and LRP6, showing that these lipid genes are also linked to hyperglycemia or diabetes." (PMID 35740449, 2022). "ABCA1 expression is reduced in diabetes and is associated with a significant accumulation of cholesterol in macrophages." (PMID 33946646, 2021). "We retrieved literature about the relationship between ABCA1 gene polymorphisms (C69T and R230C) and the risk of diabetes through PubMed, Web of Science, EMBASE, Wanfang Database, China National Knowledge Infrastructure (CNKI) and Cochrane database." (PMID 31010439, 2019). "In the current study, we analyzed the correlations between ABCA1 gene polymorphisms and patients with diabetes mellitus using a pooled analysis to obtain a powerful conclusion." (PMID 31010439, 2019). "ABCA1 R230C T allele gene mutation is a protective in decreasing the risk of diabetes in Caucasians and ABCA1 C69T gene mutation markedly influences the level of lipid metabolism in diabetic patients." (PMID 31010439, 2019). "ABCA1 R230C T allele was significantly associated with reduced the risk of diabetes (OR = 0.75, 95% CI = 0.57–0.98, P = 0.04)." (PMID 31010439, 2019). "The interaction between CAD and some acquired risk factors such as diabetes, hypertension and smoking on the DNA methylation of ABCA1 was evaluated." (PMID 30046619, 2018). "The overall rather moderate deterioration of glucose homeostasis and diabetes risk could indicate a compensatory cholesterol export via ABCA1 and ABCG1." (PMID 36527064, 2022). "The ATP-binding cassette transporter A1 (ABCA1) is likely associated with the risk of type 2 diabetes mellitus (T2DM) via β cell function modification, but the evidence on the association remains unclear." (PMID 33967955, 2021). "In addition, it needs to be taken into consideration that diabetes is also associated with a reduced macrophage expression of ABCA1 and ATP-binding cassette G1 (ABCG1), the major membrane transporters involved in RCT." (PMID 34063950, 2021). "Since HDL levels are risk factors in diabetes, ABCA1 may serve as a diagnostic marker in T2DM5,23,24." (PMID 33531564, 2021). "Few studies have examined the role of ABCA1 polymorphism (rs2065412 and rs414936) in diabetes." (PMID 32600448, 2020). "In addition, the ABCA1 gene is just one of the hosts of genetic risk factors for lipid metabolic abnormalities in the diabetes population." (PMID 31010439, 2019). "ABCA1 R230C/C230C genotypes might confers susceptibility to diabetes through insulin secretion and adipocyte function." (PMID 31010439, 2019). "In addition, the ABCA1 R230C polymorphism may play an important role in maintaining glucose-mediated insulin secretion, in turn, leads to a 4-fold increase occurrence of diabetes." (PMID 32600448, 2020). "Diabetes increases the level of unsaturated fatty acids (uFAs), which was shown to destabilize ABCA1 protein in murine macrophages and impair the ABCA1 pathway through a PKCδ-dependent pathway." (PMID 37974282, 2023). "The findings from our study will contribute in genetic pool of studies concerning ABCA1 in diabetes and diabetic dyslipidemia." (PMID 37821518, 2023). "In our study, the downregulation of ABCA1 gene was observed among patients of diabetes and diabetic dyslipidemia as compared to normal healthy individuals." (PMID 37821518, 2023). "Specifically, it should be noted that ABCG1, ABCA1 and ACSL3 were negatively, while KAT2B positively, associated with all signatures of statin use, CpG methylation and diabetes risk/status." (PMID 32612641, 2020).
diabetes (continued). "ATP-binding cassette transporter A1 (ABCA1) is a cholesterol exporter, which plays a protective role in cardiovascular disease and diabetes." (PMID 32774146, 2020). "The role of ABCA1 and cholesterol metabolism in pathogenesis of diabetes, a frequent co-morbidity of HIV infection, is also well established." (PMID 31344124, 2019). "In type 1 diabetes mellitus and diabetic apolipoprotein E knockout (apoE−/−) mice, the expression ABCA1 was downregulated in the kidney." (PMID 29681863, 2018). "Although the R230C-ATP-binding cassette A1 (ABCA1) variant has been consistently associated with HDL-C levels, its association with diabetes and other metabolic parameters is unclear." (PMID 26579206, 2015). "Although the ABCA1/R230C variant has been consistently associated with HDL-C levels, its association with diabetes and other metabolic parameters is unclear." (PMID 26579206, 2015). "Inducing diabetes with streptozotocin significantly reduced renal expression of ABCA1, ABCG1 and SR-BI." (PMID 25181357, 2014). "Secondly, inducing diabetes with streptozotocin significantly reduced renal expression of not only ABCA1 but also ABCG1 and SR-BI, and these changes preceded the development of diabetic nephropathy." (PMID 25181357, 2014). "ABCA1/ABCA7 is bound up with Alzheimer’s disease, ABCA4 is in connection with Stargardt macular degeneration, and ABCC8/SUR1 and ABCC9/SUR2 are both associated with diabetes." (PMID 35783291, 2022). "The first point of strength is that this study is the first and only study to investigate the prevalence of ABCA1 C69T (rs1800977) gene polymorphism in Saudi adults not previously diagnosed with diabetes." (PMID 36553543, 2022). "Similarly, mice with β-cell-specific deletion of Abca1 displayed impaired glucose tolerance, which worsened to substantial islet inflammation and diabetes in mice with additional deletion of Abcg1." (PMID 36527064, 2022). "Diabetes and inflammatory mediators, including hs-CRP, have also been implicated in AOX1 activity, as well as HDL-cholesterol-levels via interaction of AOX1 with the ATP-binding cassette transporter A1 (ABCA1) which is a regulator of HDL metabolism." (PMID 32041099, 2020). "Although some studies found the ABCA1 gene mutation increased the risk of diabetes, the results were negative in other people’s studies." (PMID 31010439, 2019). "Agonism of PPAR-γ coupled the uptake of oxidized low density lipoprotein to cholesterol efflux via induction of liver X receptor-α-mediated transcriptional cascade and the cholesterol efflux pump Abca1, and was beneficial in providing the atheroprotective effects in diabetes." (PMID 29503646, 2018). "The differences in regulation of ABCA1 expression under diabetic conditions might be attributed to the animal models used, type of diabetes studied, and its duration." (PMID 29036927, 2017). "Although the relationship between ABCA1 and AD has been widely investigated, how the ABCA1 R219K variant affects diabetes-related MCI has not been reported." (PMID 28824418, 2017). "It is noteworthy that ABCA1 has never been identified as a diabetes-associated gene in genome-wide association studies GWAS." (PMID 26579206, 2015). "Because none of these ABCA1 mutation carriers had diabetes, the authors suggested that carriership is a relatively mild islet susceptibility factor for diabetes by itself." (PMID 26579206, 2015). "Furthermore, ABCA1 expression is reduced in leukocytes and cultured skin fibroblasts from patients with diabetes." (PMID 24179149, 2014). "Cholesterol efflux to apoA-I is known to be essential for maintaining physiological functions in these cell types, as tissue-specific ABCA1 deletion results in foam cell formation (macrophages), diabetes (pancreatic β cells) and extremely low HDL (hepatocytes)." (PMID 25415591, 2014).